CAHM (colon adenocarcinoma hypermethylated)
Synonyms: LINC00468
Gene: Long non-coding RNA gene on chromosome 6 (163,368,306 to 163,415,456, reverse strand). Ensembl gene ENSG00000270419.
Diseases named in the same sentence as CAHM in open-access papers:
CAHM is named in the same sentence as 14 diseases in open-access papers, as found by Europe PMC text mining. Sharing a sentence is not in itself a finding about the gene and the disease. The quoted sentences say what the papers report.
adenoma (3 papers, 2014 to 2023). A neoplasm arising from the epithelium. "CAHM methylation levels were significantly higher in tumor tissues (adenoma and colon cancer) than in normal colon tissues." (PMID 37077416, 2023). "Particularly, a PCR-based region (chr6: 163,834,393–163,834,455) of CAHM demonstrated frequent methylation, with a positive rate of 81% (17/21) in adenomas and 71% (56/79) in CRC tissues." (PMID 36017498, 2022). "With the threshold of 5% methylation, the CAHM assay was positive in 2/26 normals (8%), 17/21 adenomas (81%), and 56/79 cancers (71%)." (PMID 24799664, 2014). "We therefore explored the detection of methylated CAHM sequences in bisulphite-converted DNA extracted from plasma of 220 patients who were classified by colonoscopy to include 74 normal patients, 73 with adenoma and 73 with CRC." (PMID 24799664, 2014). "Using a threshold of 3 pg methylated genomic DNA per mL plasma, methylated CAHM sequences were detected in the plasma DNA of 40/73 (55%) of CRC patients compared with 3/73 (4%) from subjects with adenomas and 5/74 (7%) from subjects without neoplasia." (PMID 24799664, 2014). "Interestingly, the frequent hypermethylation of CAHM observed in colorectal adenoma tissues is not reflected in the plasma of adenoma patients." (PMID 24799664, 2014). "Indeed, increased methylation of CAHM was also found in the plasma DNA of 55% (40/73) of CRC patients, but not in 73 adenomas (4%) and 74 subjects without neoplasia (7%)." (PMID 36017498, 2022).
breast carcinoma (3 papers, 2014 to 2023). "Examination of a broader tissue set including lung, prostate and breast cancers demonstrated significant specificity for methylation of CAHM in CRC relative to other cancers." (PMID 24799664, 2014). "The authors also detected high methylation levels of CAHM in breast cancer." (PMID 37077416, 2023). "CAHM was found to be hypermethylated in only 2 other cancer specimens, namely breast cancer (2/10, 20%), whereas it was not methylated in lung or prostate cancer samples." (PMID 24799664, 2014).
glioma (3 papers, 2021 to 2023). A benign or malignant brain and spinal cord tumor that arises from glial cells (astrocytes, oligodendrocytes, ependymal cells). "In another study CAHM overexpression inhibited glioma migration and invasion via the SPAK/MAPK pathway." (PMID 37077416, 2023). "Interestingly, in that study CAHM expression was negatively correlated with OS in primary and recurrent gliomas." (PMID 37077416, 2023). "CAHM overexpression inhibited glioma cell proliferation, colony formation, and invasion." (PMID 37077416, 2023). "Thus, CAHM plays a role in biological processed involved in glioma." (PMID 37077416, 2023). "The well-established functions of CAHM, which is also known as colorectal adenocarcinoma hypermethylated, as a prognostic biomarker in colorectal and thyroid carcinoma, and its regulation by DNMT1 in glioma cells, suggest its involvement in glioma grade, subtype, malignant behavior, and prognosis." (PMID 37666951, 2023).
colorectal adenocarcinoma (2 papers, 2014 to 2023). The most common type of colorectal carcinoma. "LOC100526820 has now been given the gene symbol CAHM, for Colorectal Adenocarcinoma HyperMethylated." (PMID 24799664, 2014).
breast tumors (1 paper, 2016). "We also found that two lncRNAs, CAHM and KCNQ1DN, are down-regulated in breast tumors compared to healthy normal controls in our study." (PMID 27597120, 2016).
colon adenocarcinoma (1 paper, 2014). "Based on the relationship between high CAHM methylation and CRC revealed by the bisulphite-tag and bisulphite deep sequencing data, the HUGO Gene Nomenclature Committee (HGNC) approved renaming of LOC105526820 as Colon Adenocarcinoma HyperMethylated (non-protein coding), gene symbol CAHM." (PMID 24799664, 2014).
colorectal adenoma (1 paper, 2014). An adenoma that arises from the colon or rectum. "In addition to observing frequent (56/79, 71%) hypermethylation of CAHM in DNA from CRC tissues relative to that from normal controls, we report that most (17/21, 81%) DNA samples from colorectal adenoma tissues likewise show hypermethylation of CAHM." (PMID 24799664, 2014). "Having developed a methylation-specific PCR (qMSP), we then demonstrate that CAHM is methylated at the sites of the qMSP primers in a high proportion of colorectal adenomas and cancers, but not in normal colorectal tissue." (PMID 24799664, 2014).
gastric cancer (1 paper, 2020). A primary or metastatic malignant neoplasm involving the stomach. "For the remaining three lncRNAs – LINC01089, TUSC8 and CAHM — the LncRNADisease2 database used computational methods and predicted they are associated with gastric cancer." (PMID 32024523, 2020).
tumor (5 papers, 2014 to 2023). "For the KEGG pathway, CAHM, DUXAP8, MKLN1-AS, and RHPN1-AS1 were all enriched in these tumor proliferation-related pathways such as Spliceosome, Cell cycle, DNA replication, and RNA transport, suggesting their important role in the tumorigenesis." (PMID 34917132, 2021). "Akt plays a role in many tumor biological processes, and the G 12/13 pathway is related to AKT, indicating that CAHM may regulate tumor-related biological processes by regulating AKT phosphorylation or dephosphorylation." (PMID 37077416, 2023). "The proportion of LncRNA-CAHM methylation in CRC stage II–IV was significantly higher than that in normal colorectal specimens (p < 0.0002), and the median CAHM methylation level in tumor colorectal specimens was 17%–40%." (PMID 37077416, 2023). "Silencing of CAHM, in addition to QKI, may therefore be important for tumor development." (PMID 24799664, 2014).
cancer (1 paper, 2014). A tumor composed of atypical neoplastic, often pleomorphic cells that invade other tissues. "Future studies could investigate the proportion of methylated CAHM as a function of the different subtypes of CRC and the clinical or phenotypic characteristics of the individuals in whom these cancers arise." (PMID 24799664, 2014).
CAHM also shares sentences with these, for which no sentence is quoted: colon cancer (1 paper); colon tumor (1); prostate carcinoma (1); thyroid cancer (1).